HIF1A (hypoxia inducible factor 1 subunit alpha)
Diseases named in the same sentence as HIF1A in open-access papers (continued):
Sharing a sentence is not in itself a finding about the gene and the disease.
cancer (continued). "Hypoxia inducible factor 1α (HIF-1α) plays a critical role in angiogenesis, metabolic reprogramming, cell replication, metastasis and cancer stem cell renewal in response to hypoxia." (PMID 37296897, 2023). "Further studies are required to verify the efficacy of the HDAC8-mediated deacetylation of HIF-1α in other cancer cell lines." (PMID 36831463, 2023). "Hypoxia-inducible factor-1α (HIF-1α) has been shown to be involved in cancer metastasis in several cancer types." (PMID 36766555, 2023). "In vitro, as little as three hours of hypoxia is sufficient to stabilize the HIF-1α protein, which is involved in cell proliferation, invasion, angiogenesis and metastasis of cancer cells." (PMID 37798384, 2023). "Previous research exploring the roles of CPT1s in other cancer types has revealed that CPT1s expression is positively associated with hypoxia, and CPT1A has been confirmed as the direct target of HIF1α." (PMID 37078750, 2023). "Experiments in a series of cancers demonstrated that HIF-1α provokes EMT phenotype or characteristics by directly augmenting EMT-related transcription factors like zinc finger E-box binding homeobox (ZEB), Slug, Twist, and Snail." (PMID 36814597, 2023). "We and other researchers have shown that hypoxia-inducible factor (HIF)-1α promotes cancer aggressiveness through cancer cell proliferation, invasion, and metastasis." (PMID 37511305, 2023). "The enzyme catalyzing this reaction is acetyl CoA synthase −2, an important target gene of HIF-1α and is integral to cancer cell survival and proliferation under hypoxic conditions." (PMID 36891273, 2023). "Significantly, HIF1α contributes to the development of drug resistance to radiotherapy and chemotherapy in cancer treatment." (PMID 37894802, 2023). "And in recent years, the miRNA/HIF-1α axis was comfirmed to be an important regulatory role in malignant tumors." (PMID 37938614, 2023). "CAIX is a direct HIF-1α target that is induced by aerobic glycolysis in order to allow cancer cells to adapt to the acidic microenvironment." (PMID 37194791, 2023). "Inhibition of HIF-1α with the small molecule KC7F2 has been explored as a potential avenue for cancer therapy." (PMID 36980629, 2023). "Dysregulations of the pathway HIF-1α lead to several diseases including cardiovascular disease, cancer, and AD." (PMID 37359008, 2023). "The previous study has demonstrated upregulated HIF1A expression in breast tumors compared with normal breasts and served as a potential prognostic biomarker for cancer recurrence." (PMID 36994412, 2023). "HIF1α promotes transcription of genes responsible for TIC activity and hypoxia signatures are associated with cancer stemness and poor survival for patients with LUAD." (PMID 38106234, 2023). "Cancer cells respond to hypoxia in the microenvironment through transcription of many genes, including “hypoxia-inducible factor-1α” (HIF-1α), heat-shock proteins (HSPs), and angiogenesis-related molecules, such as VEGF." (PMID 37445908, 2023). "Loss of the function of tumor suppressor protein VHL (pVHL) leads to accumulation and constitutive activation of hypoxia inducible factor 1α (HIF-1α) in cancer cells." (PMID 38273861, 2023). "Applications that either directly or indirectly decrease HIF1-α expression and are utilized in combination with other anti-cancer therapies have demonstrated an increase in response to radiotherapy and chemotherapy." (PMID 36539586, 2023). "Another example can be seen with transcription factor HIF-1α, promoting the expression of various glycolytic enzymes, which is stabilized by the loss of E3 ligase VHL in cancer cells and consequently contributes to aerobic glycolysis." (PMID 37176148, 2023). "Mounting studies have demonstrated that the EMT of cancer cells can be enhanced by overexpression of HIF1α." (PMID 37382594, 2023). "YTHDF2 upregulation by HIF-1α promotes cancer cell proliferation in acute myeloid leukaemia (AML) and lung squamous carcinogenesis (LUSC)." (PMID 36859310, 2023).
cancer (continued). "One research group has shown that in four cancer cell lines of different origin, curcumin decreased glucose uptake, lactate production, and protein levels of HIF1α, PKM2, and p70S6K—the target of mTOR." (PMID 38001865, 2023). "In this study, we elucidated a distinct mechanism governing HIF-1α degradation in chronic hypoxic cancers, proposing its variability based on cancer metabolism and VHL activity." (PMID 37777750, 2023). "As such, survivin, hif-1α and p27KIP1 are potential targets for developing effective anti-cancer therapy against NSCLC." (PMID 37534226, 2023). "It is commonly observed that solid tumors exhibit elevated levels of HIF‐1α, which is also related to the clinical outcome in various types of cancer." (PMID 37701531, 2023). "Separately, HIF-1α was reported to upregulate PDL1 expression in cancer cells, facilitating escape from CTL-mediated lysis and promoting CTL apoptosis." (PMID 37180129, 2023). "The c-myc and HIF-1α are important promoters of oncogenes in the carbohydrate metabolism of cancer cells." (PMID 36851737, 2023). "In this regard, HIF1α drives metabolic changes that allow cancer cells to produce more ATP while maintaining a low NAD(P)H/NAD(P)+ ratio required to ensure mitochondrial activity." (PMID 36769044, 2023). "Hypoxia inducible factor-1α (HIF-1α) is a nuclear transcription factor produced by cancer cells adapting to hypoxia environments." (PMID 37599427, 2023). "Recently, it was also demonstrated the role of Notch/HIF-1α signaling in different processes like liver regeneration, angiogenesis, and cancer epithelial-mesenchymal-transition." (PMID 37965556, 2023). "A highly active glucose metabolism and overexpression of HIF-1α have been observed in GBM, and high levels of HIF-1α are associated with advanced cancer progression and poor clinical outcomes in GBM." (PMID 38098117, 2023). "An active component of Angelica gigas was reported as having an anti-cancer effect by down-regulating the protein level of HIF-1α in vitro and in vivo." (PMID 36673369, 2023). "HIF-1α is the most functional transcription factor in cancer, helping the cells to survive and proliferate in stressful hypoxic conditions." (PMID 37762231, 2023). "Under hypoxia, HIF-1α increases the transcriptional expression of various genes that are involved in cancer progression, metastasis, angiogenesis, and resistance to therapy." (PMID 37242466, 2023). "Cytoplasmic HIF1α expression ranged from 0–98% (median 47), while nuclear expression ranged from 0–27% (median 0%) of cancer cells." (PMID 36900270, 2023). "A previous report suggested that HIF-1α and c-myc in cancer cells can regulate the lactic acid fermentation pathway and the glutamine metabolism pathway." (PMID 36851737, 2023). "The activation of HIF1α participates in the transcription of genes involved in important cancer biology, including cell survival, angiogenesis, glucose metabolism, and invasion." (PMID 37957150, 2023). "As a result, AMPK indirectly inhibits HIF-1α activity and makes cancer cells fragile during radiotherapy." (PMID 37491250, 2023). "It was discovered through research into the impact of miR-224 on the growth of non-small cell lung cancer induced by cancer-associated fibroblast (NSCLC) that overexpression of SIRT3 can suppress miR-224 by activating AMPK and deactivating mTOR/HIF-1α." (PMID 37175631, 2023). "CircRNF20 also plays a role in cancer progression through stabilizing HIF1α and downstream signaling in breast cancer cells." (PMID 37583933, 2023).
cancer (continued). "This was purported to be via the HIF-1α pathway and is an example of aspirin as a possible therapeutic adjunct in cancer treatment." (PMID 37720350, 2023). "HIF-1α activation and subsequently Drp1Ser616 phosphorylation are involved in mitochondrial fission; however, these findings were derived from cancer cells or the pancreas." (PMID 38203413, 2023). "In various cancer types, the overexpression of miR-210 is regulated in a hypoxia-inducible factor-1a (HIF-1α)-dependent manner." (PMID 37242681, 2023). "HIF‐1α, as an important regulator of cell adjustment to hypoxia, is frequently upregulated in cancers dhypoxia in tumors or the activation of various oncogenic pathways." (PMID 36971046, 2023). "Cancer cells activate HIF-1α signaling to manage hypoxic stress in the TME and directly regulate glycolysis." (PMID 37108468, 2023). "Our data demonstrated the synergistic inducing EMT effect of IL-6 combined with hypoxia via the IL-6/STAT3/HIF-1α autocrine loop, which contributes to understanding cancer progression and invasiveness, and developing a feasible therapeutic strategies for EOC." (PMID 36814597, 2023). "3D culture has proven to be a useful tool to understand how cancer cells respond to redox stress since they are exposed to an oxygen gradient with a hypoxic core where HIF1α activates." (PMID 36769044, 2023). "Of clinical relevance, we observed that levels of HIF-1α in EVs from COPD subjects who subsequently developed cancer are significantly higher than in COPD subjects who remained cancer-free." (PMID 37838700, 2023). "HIF-1α protein was detected in VHL-deficient renal epithelial cells, and also ccRCC, suggesting its implications in cancer progression." (PMID 37176098, 2023). "Hypoxia inducible factor‐1α (HIF‐1α) plays a critical role in cellular adaptation to hypoxia and it is a potential therapeutic target for anti‐cancer drugs." (PMID 37401167, 2023). "The median percentage of HIF1α + cancer cells was 60% in cases with high PD-L1 cancer cell expression vs. 20% in cases with low (p < 0.01)." (PMID 37067635, 2023). "Accordingly, the profound involvement of HIF-1α in stemness presents it as a potential therapeutic target to limit the action of CSCs in cancer." (PMID 36846589, 2023). "Consistently, HIF-1α is overexpressed in multiple cancers, such as breast, colon, lung, and prostate carcinomas, and it has been recognized as an attractive target for anti-cancer therapy." (PMID 36831463, 2023). "Accordingly, pharmacological targeting of the HIF-1α signaling pathways has been recognized as a promising strategy for cancer therapy in the recent years." (PMID 37305566, 2023). "Hypoxia is known to closely contribute to chemoresistance in cancers and HIF1A is an important target for hypoxia-driven drug resistance." (PMID 36611208, 2023). "HIF-1α is crucial regulator of cellular response to hypoxia as it affects most of “hallmarks” of cancer." (PMID 36939902, 2023). "For example, iron supplementation (40 μM of FeCl2) dramatically reduces HIF-1α levels in cancer cells in vitro." (PMID 36768740, 2023). "In the hypoxic microenvironment, the accumulation of HIF1-α promotes the glycolysis, maintaining the survival of the cancer cells." (PMID 37599427, 2023). "Hypoxia can activate hypoxia-inducible factor 1α (HIF1α), which upregulates PD-L1 expression on dendritic cells and cancer cells, leading to immunosuppression." (PMID 37790761, 2023). "In LKB1- and AMPK-deficient cells, HIF-1α is upregulated to provide energy and preserve the cellular shape of LKB1-AMPK-deficient cells (e.g., some types of cancer cells)." (PMID 37626660, 2023). "Cancer plasticity is a newly recognized hallmark of cancer and induced or regulated not only by a vaste array of transcription factors, by the EMT-specific ones but also by less specific ones such as HIF1A or STAT1/2." (PMID 36754910, 2023).
cancer (continued). "Hypoxia is a significant driver of cancer invasion and metastasis, and HIF-1A and HIF-2A, as central regulators of the cellular response to hypoxia, play an essential role in this process." (PMID 36937833, 2023). "Hypoxia-activated HIF-1α helps hypoxic cancer cells to overcome energy stress by inducing angiogenesis." (PMID 36761981, 2023). "The relationship between HIF-1α dependent regulation of fatty acid synthesis and cancer cell progression has been identified." (PMID 37087475, 2023). "Hypoxia-inducible factor-1α (HIF-1α) is the central mediator in the adaptation of cancer cells to hypoxia in hypoxic niches." (PMID 36846589, 2023). "Hypoxia inducible factor 1 subunit alpha (HIF-1-a) is the principal molecular mediator of the hypoxic response in cancer whereas EWSR1::FLI1 constitutes the oncogenic driver of EwS." (PMID 36915100, 2023). "Since fatty acid synthesis is an oxygen-consuming process, cancer cells in hypoxic environments often upregulate the uptake of external lipids via HIF1α instead of de novo synthesis." (PMID 37443779, 2023). "Hypoxia-inducible factor-1 alpha (HIF-1α) is a transcription factor that, in an oxygen-free environment, upregulates genes involved in cancer progression." (PMID 38136311, 2023). "The HIF1-α expression has been well demonstrated it played a vital role in cancer progression, angiogenesis, and metastasis." (PMID 37372967, 2023). "Hypoxia-inducible factor-1α (HIF-1α) can accelerate cancer malignancy by inducing hypoxia-dependent expression of various genes." (PMID 38066600, 2023). "STC1 can induce the adaptive response of human cancer cells to hypoxia by regulating hypoxia-inducible factor-1-α (HIF-1α), and is abnormally expressed in a variety of cancer types." (PMID 37576511, 2023). "Meanwhile, HIF-1α was considered a critical transcription factor in cancer progression and target therapy for cancers." (PMID 37215053, 2023). "HIF-1α is activated in cancer, because of genetic defects, or in low oxygen tensions, and is responsible for the transition from oxidative phosphorylation to aerobic glycolysis." (PMID 37553596, 2023). "We used a computational analysis and identified the BIRC5/HIF1A/FLT4 oncogenes as being highly upregulated in NSCLC and associated with cancer progression and poor prognoses." (PMID 37509650, 2023). "In particular, SIRT1 is known to control the activity of HIF-1α under hypoxic condtions in various cancers." (PMID 37777750, 2023). "The HIF 1 alpha and 2 alpha roles are very distinctive but HIF-1α majorly mediates the transcription of many genes in cancer." (PMID 37842368, 2023). "ccRCC is characterized by the loss of the VHL gene and further overexpression of hypoxia-inducible factor 1 alpha (HIF-1α), involved in cancer cell metabolic reprogramming." (PMID 37176098, 2023). "One potential pathway of drug resistance is the metabolic adaptation of hypoxic cancer cells to HIF-1α inhibition." (PMID 37568758, 2023). "In RCC, HIF-1α controls cancer cell metabolism, by increasing glucose uptake, through glycolytic and pentose phosphate pathways." (PMID 37176098, 2023). "During glucose metabolism, activation of mTOR signaling in cancer cells can enhance the expression of genes related to glucose uptake and glycolysis through upregulation of the hypoxia-inducible factor 1α (HIF1α)." (PMID 37259304, 2023). "ANGPTL4 has been extensively studied in cancer research and reported to increase upon hypoxia and co-localize with HIF-1α." (PMID 38016947, 2023). "The transition metal cobalt(II) chloride can mimic hypoxia by upregulating and stabilising HIF-1α, which plays an important role in the cell cycle and survival of cancer cells." (PMID 36879003, 2023).
cancer (continued). "Based on the oncology array results, we demonstrated that melatonin exerts its anti-cancer effect by down-regulating the HIF-1α and NF-κB pathways and downstream pathways, including Bcl-2, leading to cell cycle arrest and apoptosis induction in the UBUC cells." (PMID 37086261, 2023). "Clinical samples from cervical and other cancer also showed high cytoplasmic accumulation of SUMOylated pH3(Ser10) in the acutely hypoxic zones (identified by high HIF1a expression)." (PMID 36980166, 2023). "The interaction between HIF-1α and Notch signaling was elucidated in the hypoxic cellular response of cancer and RA synovial fibroblast cells." (PMID 38022508, 2023). "The finding that ROS-lowering doses of antioxidants increased HIF1α levels was surprising because VitC has been shown to reduce HIF1α levels and transcriptional targets in some cancer cells." (PMID 37651203, 2023). "Cancers with an in situ component had higher HIF-1α histoscores (IRR [95% CI]: 4.84 [0.93–20.2], p = 0.04); associations with other clinical parameters were not significant." (PMID 37166494, 2023). "Cancer cells respond to this oxygen shortage by overexpressing hypoxia-inducible factors, such as HIF-1α, which regulates a large number of target genes involved in invasion, extravasation, and EMT." (PMID 37686617, 2023). "Accordingly, IDF-11774, a drug targeting HIF-1α, holds promise for revolutionizing cancer therapeutics." (PMID 38140111, 2023). "Usually, this occurs in conditions of low oxygen tension, but it has been noted to occur in normoxic contexts such as cancer (i.e., Warburg effect) and degenerative/inflammatory diseases where HIF-1α plays a mediating role." (PMID 37134114, 2023). "Many studies have shown that blocking HIF1α enhances the efficacy of chemo-, radio- and immuno-therapies and therefore becomes a potential therapeutic strategy for cancer." (PMID 37020036, 2023). "Here, we demonstrated that the shuttle of HIF-1α contained in EVs from cancer-free individuals activates the transcription of CXCR4 that in turn increases the frequency of mesenchymal and disseminating CD133+CXCR4+ MICs." (PMID 37838700, 2023). "MiR-210 serves as downstream of HIF-1α, which is frequently upregulated in different cancers under hypoxia." (PMID 36939902, 2023). "As HIF-1α plays a pivotal role in cancer cell metabolism and metastasis, we also evaluated cell migration and invasion using a Transwell assay." (PMID 38140111, 2023). "This genetic change can induce BHLHE41/DEC2 expression during cancer development under HIF-1α expression; however, in this study the direct effects of BHLHE41/DEC2 were not examined." (PMID 37511489, 2023). "For example, mROS has been shown to promote the activation of HIF1α signaling via stabilizing the HIF1α protein, which is required for cancer progression." (PMID 37644092, 2023). "It has been demonstrated that HIF-1α can interact with the Notch target gene to regulate its signaling in cancer stem cells." (PMID 37807067, 2023). "The substantial impact of HIF-1α on hallmarks of cancer, stemness, and chemoresistance makes it an attractive target in cancer therapy." (PMID 36846589, 2023). "CircRNAs have also been shown to interact with c-myc and HIF1-α in several cancer models, suggesting a potential role for circRNAs in cancer metabolism." (PMID 36899402, 2023). "For example, HIF-1α promotes the transduction of P-gp, a drug efflux pump, that can extrude chemotherapeutic drugs from the cancer cells, thereby reducing their effectiveness." (PMID 37981704, 2023). "The curcumin-loaded nanoparticles were demonstrated to effectively decrease the expression of hypoxia-inducible factor 1-alpha (HIF-1α) and deplete glutathione, thereby enhancing the vulnerability of cancer cells to PDT." (PMID 37623653, 2023).